DKK2 (dickkopf Wnt signaling pathway inhibitor 2)
Diseases named in the same sentence as DKK2 in open-access papers (continued):
Sharing a sentence is not in itself a finding about the gene and the disease.
craniosynostosis (1 paper, 2015). Craniosynostosis is defined as the premature fusion of one or more cranial sutures leading to secondary distortion of skull shape resulting in skull deformities with a variable presentation. "DKK2 was chosen to validate as it was identified with the more relaxed criteria; thus, FDR 0.15 genes may still be biologically relevant in craniosynostosis." (PMID 25987937, 2015).
endometrioid carcinomas (1 paper, 2018). "In our series, hypermethylation of the Wnt antagonists (DKK1, DKK2, SFRP1, SFRP4, SFRP5, and WIF1) were observed with a significant prevalence in mucinous and endometrioid carcinomas." (PMID 29882921, 2018).
Ewing family tumor (1 paper, 2009). "We found increased expression of DKK2 but decreased expression of DKK1 in Ewing family tumor (EFT) cells." (PMID 19247449, 2009).
glioma (1 paper, 2015). A benign or malignant brain and spinal cord tumor that arises from glial cells (astrocytes, oligodendrocytes, ependymal cells). "The inhibited DKK2 expression lead to up-regulation of the protein levels of Bcl2 and c-Myc in glioma cells." (PMID 26656471, 2015).
medulloblastoma (1 paper, 2014). A malignant, invasive embryonal neoplasm arising from the cerebellum. "In accord with previous reports, we identified distinct groups of co-expressed genes that were highly enriched for WNT signalling in WNT medulloblastoma, (including DKK1, DKK2, DKK4, WIF1, LEF1 and WNT16)." (PMID 25412507, 2014).
myocardial infarction (1 paper, 2018). Gross necrosis of the myocardium, as a result of interruption of the blood supply to the area, as in coronary thrombosis. "Wnt ligands have been shown to be upregulated alongside their feedback regulators Dkk1 and Dkk2 as a response in mouse models with induced cardiac injuries such as myocardial infarction." (PMID 30526659, 2018).
neuroblastoma (1 paper, 2018). Neuroblastoma (NB) is the most common solid, extracranial childhood tumor. "Analysis of genes that are increased with retinoic acid induced differentiation of neuroblastoma cells (NGRF, NF68, NTRK1, SYP, MAP2, NEFM, DKK2) showed that all were elevated after 72 hours Wnt3a/Rspo2 treatment." (PMID 29505958, 2018).
neuropathy (1 paper, 2017). A disorder affecting the nervous system that manifests with pain, tingling, numbness, and/or muscle weakness. "Finally, we further examined the effect of the overexpression of DKK2 gene on CNI-induced neuropathy and angiopathy." (PMID 29259207, 2017). "In light of critical role of neuropathy and angiopathy in the pathogenesis of radical prostatectomy-induced ED, reprogramming of damaged erectile tissue toward neurovascular repair by use of a DKK2 therapeutic protein may represent viable treatment option for this condition." (PMID 29259207, 2017).
pancreatic adenocarcinoma (1 paper, 2021). "In pancreatic adenocarcinoma, GATA6 directly binds to the DKK2-promotor leading to a down-regulation of its expression and, therefore, reduces its suppressive effect on the oncogenic Wnt pathways." (PMID 33300112, 2021).
Peri-Implantitis (1 paper, 2020). An inflammatory process with loss of supporting bone in the tissues surrounding functioning DENTAL IMPLANTS. "Collectively, these results indicate that miR-128 promotes osteogenic differentiation of rBMSCs by targeting DKK2, which may provide a promising approach to the treatment of peri-implantitis." (PMID 31985779, 2020). "Hence, we could hypothesize that the inhibitory effect of IL-1β on miR-128 expression might be one of the reasons for repressed osteoblast differentiation in peri-implantitis and that miR-128 might play a positive role during osteogenic differentiation by regulating DKK2 expression." (PMID 31985779, 2020). "The authors of the present study concluded that miR-27a could promote osteogenesis and angiogenesis simultaneously by targeting DKK2 and the secreted frizzled-related protein 1 (SFRP1) in a canine peri-implantitis model." (PMID 31985779, 2020).
pituitary adenomas (1 paper, 2015). "A review of 13 whole genome approaches in pituitary tumors with the goal of identifying Wnt family inhibitors showed that expression of WF1, SFRP2, FRZB, SFRP4, DKK2, and SOSTDC1 genes is decreased in pituitary adenomas compared to normal pituitary tissue, while that of SFRP1 and SFRP4 is increased." (PMID 25834571, 2015).
renal cell carcinoma (1 paper, 2015). "DKK2 expression was epigenetically silenced by methylation in renal cell carcinoma (RCC) and the methylation frequency of the DKK2 gene promoter region is higher in RCC patients with higher grades and stages of the disease." (PMID 26656471, 2015).
Retinal hemorrhage (1 paper, 2014). Bleeding located within the retina. "Thus, we speculate that suppressed vessel regression because of DKK2 overexpression during hyperoxia may lessen the relative hypoxic condition present upon return to normoxia, resulting in both less tuft formation and a lower incidence of retinal hemorrhage." (PMID 24091497, 2014).
serous ovarian cancer (1 paper, 2021). "In addition, Dkk2 expression differed significantly (p<0.001) between low and high grade serous ovarian cancer." (PMID 33679613, 2021).
Stroke (1 paper, 2010). Sudden impairment of blood flow to a part of the brain due to occlusion or rupture of an artery to the brain. "Therefore, in the setting of stroke recovery, elevated levels of secreted DKK2 might limit neuronal apoptosis to preserve neuron survival and improve tissue integrity." (PMID 20509949, 2010).
triple-negative breast carcinoma (1 paper, 2025). An invasive breast carcinoma which is negative for expression of estrogen receptor (ER), progesterone receptor (PR), and human epidermal growth factor receptor 2 (HER2). "In addition, GAS5 also sponges miR-221-3p, which downregulates DKK2, an essential inhibitor of the Wnt/β-catenin pathway, specifically in triple-negative breast cancer (TNBC)." (PMID 39958058, 2025).
tumor (56 papers, 2009 to 2026). "In contrast, lymph node metastases had greater tumor cell diversity including novel tumor states enriched with gene signatures associated with cancer stemness and metastasis (e.g., DKK2, FUT9, DIAPH321–23)." (PMID 41279557, 2025). "Our study found that LINC00326/miR-657/DKK2 axis signaling blocks tumor-associated functions in NSCLC cells by targeting the Wnt/β-catenin pathway." (PMID 36747258, 2023). "LINC00326/miR-657/DKK2 axis signaling blocked tumor-associated functions in NSCLC cells through the targeting Wnt/β-catenin pathway." (PMID 36747258, 2023). "Our recent study demonstrated that in human CRC tumor samples expressing high levels of DKK2, DKK2 blockade caused stronger activation of tumor infiltrated CD8+ T cells in ex vivo culture." (PMID 32559853, 2020). "Here, our recent study demonstrated that in human CRC tumor samples expressing high levels of DKK2, DKK2 blockade caused stronger activation of tumor infiltrating CD8+ T cells in ex vivo culture." (PMID 32559853, 2020). "Taken together with the genotyping data, our results indicate that this transcriptionally inactive DKK2 allele was being selectively retained in the tumor when heterozygous HCC patients exhibited a LOH during tumorigenesis." (PMID 27203079, 2016). "We conducted haplotype analysis of the DKK2 promoter sequence and found that a transcriptionally inactive DKK2 allele was selectively retained in the tumor tissues." (PMID 27203079, 2016). "Retention of this allele in LOH was associated with reduced DKK2 transcription in the HCC tumor tissues." (PMID 27203079, 2016). "Taken together, the genotyping and functional findings are consistent with the hypothesis that DKK2 is a tumor suppressor; by selectively retaining a transcriptionally inactive DKK2 allele, the reduction of DKK2 function results in unchecked Wnt/β-catenin signaling, contributing to HCC oncogenesis." (PMID 27203079, 2016). "Mechanistically, NAT10-mediated ac4C modification of DKK2 mRNA in tumor cells maintains DKK2 mRNA stability and promotes DKK2 secretion." (PMID 41542770, 2026). "Here, we found that NAT10 promotes DKK2 secretion by tumor cells, which increases cholesterol production and impairs the cytotoxic function of CD8+ T cells." (PMID 41542770, 2026). "Collectively, these results suggest that NAT10 induces the secretion of DKK2 by tumor cells and that DKK2 serves as an immune suppressive factor that restricts the recruitment of CD8+ T cells and impairs their cytotoxic function in CRC." (PMID 41542770, 2026). "Here, we reveal an unexpected immune-evasion mechanism, in which tumor-intrinsic NAT10 orchestrates CD8+ T cell dysfunction via the epigenetic regulation of DKK2." (PMID 41542770, 2026). "Our study found that the metabolite 5-aminovaleric acid produced by Fusobacterium mortiferum significantly inhibits the expression of the tumor suppressor DKK2." (PMID 40340623, 2025). "Currently, research on DKK2 primarily focuses on tumors, with several papers reporting abnormal expression of DKK2 in tumor tissues." (PMID 38178019, 2024). "It is known that DKK2 antagonizes Wnt signaling, thus, inactivation of DKK2 increases Wnt activity with accelerating tumor progression, and activation of the Wnt/β-catenin pathway has been documented in NSCLC." (PMID 36747258, 2023). "Through in-depth research on lncRNA and miRNA, it was found that LINC00326 targets the miR-657/DKK2 axis signaling and blocks tumor-related functions in NSCLC cells through the Wnt/β-catenin pathway." (PMID 36747258, 2023). "DKK2 levels were closely associated with the TNM stage, tumor differentiation, and lymphatic metastasis in NSCLC patients." (PMID 36747258, 2023). "The anti-tumor effect of MEG3 in ESCC was related to MEG3-miR-4261 axis regulating the dickkopf-2 (DKK2) and Wnt/β-catenin signaling." (PMID 35645836, 2022).
tumor (continued). "The 50 most variable downregulated genes included the cytochrome P450 family 24 subfamily A member 1 (CYP24A1), the onco‐channel TRPV6, and DKK2 (i.e., a Wnt mediator of tumor immune evasion)." (PMID 35079680, 2022). "Loss of APC in intestinal cancer cells or loss of PTEN in melanoma cells has also been shown to induce DKK2 expression, which coordinates tumor immune evasion via LRP5 and suppression of STAT5 signaling." (PMID 35204808, 2022). "Lower Dkk2 expression levels correlated with tumor progression and advanced tumor stages (FIGO III-IV)." (PMID 33679613, 2021). "By treating mice with the DNA methyltransferase inhibitor 5- aza-2′-deoxycitidine (decitabine) in order to re-establish Dkk2 expression in mice tumor growth was impaired." (PMID 33679613, 2021). "Regarding a role in cancer and in accordance with its dual performance in Wnt pathway regulation, both functions, as oncogene and tumor suppressor, have been attributed to DKK-2." (PMID 34451907, 2021). "We found that DKK2 blockade retarded tumor progression by increasing cytotoxic immune cell activation and suppressing tumor angiogenesis at the late tumor progression stage." (PMID 32559853, 2020). "The modulatory effects of neoadjuvant treatment in connection with DKK2 expression are not fully understood, but when considering DKK2 as a tumor marker, it is necessary to see it in the context of neoadjuvant therapy." (PMID 32075129, 2020). "In the study by Wang and colleagues, DKK2 expression decreased under prolonged stimulation with 5-fluourcil leading to an increased Wnt/b-catenin signaling and consecutive tumor progression." (PMID 32075129, 2020). "Analysis of tumor sections revealed that the VEGFR blockade showed a strong inhibitory effect on neovascularization compared to the control IgG group or DKK2 blockade group." (PMID 32559853, 2020). "Based on this, our study provided a novel therapeutic approach combining VEGFR blockade and DKK2 blockade, which target the tumor vasculature and boosting immune cells’ killing capacity to help to overcome immunotherapy resistance." (PMID 32559853, 2020). "Based on DKK2 mRNA levels in tumor sections, the samples were divided into the DKK2high and DKK2low groups." (PMID 32559853, 2020). "Analysis of tumor-infiltrating lymphocytes showed that DKK2 blockades led to increased levels of GZMB in tumor-infiltrating CD8+ T cells and NK cells." (PMID 32559853, 2020). "Both DKK2 blockade and VEGFR blockade showed significant tumor-suppressive effects, and the VEGFR blockade demonstrated a superior anti-tumor effect compared to the DKK2 blockade." (PMID 32559853, 2020). "In this study, we examined the effects of the DKK2 antibody on tumor progression and microenvironments in human CRC samples and mouse CRC models." (PMID 32559853, 2020). "Unexpectedly, we found that there is a significant reduction of tumor neovascularization in the anti-DKK2 antibody treatment group." (PMID 32559853, 2020). "Meanwhile, we showed that the DKK2 blockade has the same anti-tumor effects in the KrasG12D/+; Apcfl/fl mice." (PMID 32559853, 2020). "Given that the DKK2 blockade had insignificant effects on tumor angiogenesis at the early stages of tumor progression, most of the anti-tumor effects of DKK2 blockade are likely the results of its effects on modulation of tumor immune microenvironments." (PMID 32559853, 2020). "DKK2 blockage showed a stronger effect on tumor suppression than this sub-optimal dose of anti-VEFGR and extended survival." (PMID 32559853, 2020). "So far, it has been assumed that DKK2 is a Wnt-antagonist and that, accordingly, inactivation of DKK2 increases Wnt activity with accelerating tumor progression." (PMID 32075129, 2020). "Our study provided a novel therapeutic approach combining VEGFR blockade and DKK2 blockade, which target the tumor vasculature and boosting immune cells’ killing capacity to help to overcome immunotherapy resistance." (PMID 32559853, 2020).
tumor (continued). "The effects of DKK2 blockade on tumor proliferation, apoptosis, and neovascularization were assessed." (PMID 32559853, 2020). "DKK2 not only regulates tumor cell proliferation, invasion, and apoptosis directly, but also modify tumor microenvironment such as angiogenesis." (PMID 31372243, 2019). "Contrarily, tumor immune evasion by Dickkopf-related protein 2 (DKK2), with LRP5, is thought to act independently of the Wnt/β-catenin pathway, via inhibition of STAT5 signaling." (PMID 31167446, 2019). "Due to the negative relationship between the expression of DKK2 and clinical prognosis, we intended to explore the biological functions of DKK2 in tumor cells." (PMID 31583260, 2019). "Noteworthy, the DKK gene DKK2 also showed a significant enrichment in the cancerous stroma of some tumour types." (PMID 30631061, 2019). "Univariate Cox regression analysis showed that DKK2 expression, tumor size, AJCC stage classification, and liver metastasis status are significantly associated with overall survival." (PMID 31583260, 2019). "We also observed that the administration of anti-DKK2 antibody extended the survival of tumor-bearing mice in the LLC tumor model." (PMID 31372243, 2019). "Mechanistically, tumor cells secrete DKK2 that binds its receptor LRP5 inducing interactions between the intracellular domain of LRP5 and STAT5; while STAT5-phosphorylation was not precluded, STAT5 nuclear localization was impeded in cytotoxic cells." (PMID 31766350, 2019). "We found that the mRNA expression level of DKK2 in tumor tissue is evidently higher than that in adjacent tissue especially in PDAC, which suggested that DKK2 is remarkably upregulated in PDAC tissue." (PMID 31583260, 2019). "The monoclonal antibody-mediated ablation of DKK2 impeded tumor progression and enhanced the effects of PD-1 blockade." (PMID 31372243, 2019). "DKK2 blockade introduced by anti-DKK2 antibody suppressed tumor growth and enhanced the effects of cytotoxic immune cells in APC mutant NSCLC, in consistent with the previous study in colorectal cancer." (PMID 31372243, 2019). "When analyzing the correlation between DKK2 and clinical parameters, we found that the expression of DKK2 positively correlated with tumor differentiation." (PMID 31583260, 2019). "Consistent with the immunostaining results, flow cytometry analysis of tumor-infiltrating lymphocytes (TILs) showed that anti-DKK2 antibody treatment increase the percentage of GZMB+ T cells." (PMID 31372243, 2019). "We monitored tumor size every other day, and found that the tumor burden was decreased dramatically in Dkk2 knockdown group." (PMID 31372243, 2019). "IHC and hematoxylin & eosin (H&E) staining were carried out to analyze DKK2 expression and tumor features of the xenografts nude mice, respectively." (PMID 28467796, 2017). "While this study was in progress, others studying different cancer types have reported that DKK2 functions as a tumor suppressor gene." (PMID 27203079, 2016). "Macroscopically, numbers of tumor nodules detectable on the liver surface were significantly increased in Dkk2−/− compared to WT mice." (PMID 25826080, 2016). "On average the Dkk2−/− livers contained average 16 tumor nodules (n = 11) whereas the age matched, WT littermates contained average only 7.4 tumor nodules (n = 10)." (PMID 25826080, 2016). "Livers of Dkk2−/− and WT mice were sacrificed at 9 months of age to investigate morphological changes during tumor development." (PMID 25826080, 2016). "We also performed direct sequencing to determine the haplotypes of individually cloned genomic DNA fragments from the blood, tumor adjacent tissue, and tumor tissue of 16 HCC patients who were heterozygous for DKK2." (PMID 27203079, 2016). "Dkk2−/− tumor cells showed a significant deregulation of stemness genes associated with enhanced colony forming properties." (PMID 25826080, 2016).